OPN5 (opsin 5)
Description:
G protein-coupled photoreceptor that selectively activates G(i) protein in response to light in the retina (By similarity). Activation occurs when the opsin-bound cis-retinal chromophore absorbs a photon and isomerizes to all-trans-retinal, inducing a conformational change in the opsin that triggers a G protein-mediated phototransduction cascade. Acts as a bistable protein with absorption peaks at 380 nm (UVA light) and 470 nm (blue light), allowing photoreversible regeneration of the cis-retinal chromophore after stimulation. Required for the light-response in the inner plexiform layer, and contributes to the regulation of the light-response in the nerve fiber layer, via phosphorylated DAT/SLC6A3 dopamine uptake. Involved in local corneal and retinal circadian rhythm photoentrainment via modulation of the UVA light-induced phase-shift of the retina clock. Acts as a circadian photoreceptor in the outer ear and vibrissal pads, via modulation of circadian clock-gene expression in response to violet light during the light-to-dark transition phase and night phase of the circadian cycle. Required in the retina to negatively regulate hyaloid vessel regression during postnatal development via light-dependent OPN5-SLC32A1-DRD2-VEGFR2 signaling. Involved in the light-dependent regulation of retina and vitreous compartment dopamine levels. Mediates violet light-accelerated wound healing in corneas, being transiently expressed following physical injury (By similarity).
Synonyms: GPR136; PGR12; TMEM13; neuropsin; dJ402H5.1; GRP136
Tractability: Small molecule: it belongs to a druggable protein family. Antibody: UniProt places it where antibodies can reach, with high confidence; its Gene Ontology location is reachable by antibodies, with high confidence; UniProt predicts a signal peptide or a membrane-spanning region.
Target class: Opsin; Membrane receptor; Family A G protein-coupled receptor
Gene: Protein-coding gene on chromosome 6 (47,781,982 to 47,832,780, forward strand). Ensembl gene ENSG00000124818.
Subcellular location: Cell membrane
Pathways (Reactome):
Signal Transduction: G alpha (i) signalling events; Opsins
Gene Ontology:
Molecular function: 11-cis retinal binding; G protein-coupled photoreceptor activity; G protein-coupled receptor activity
Biological process: cellular response to UV-A; phototransduction, UV; adenylate cyclase-inhibiting G protein-coupled receptor signaling pathway; cellular response to light stimulus; entrainment of circadian clock by photoperiod; G protein-coupled receptor signaling pathway; hyaloid vascular plexus regression; phototransduction; positive regulation of wound healing; detection of visible light; visual perception
Cellular component: cytoplasm; plasma membrane; photoreceptor outer segment; membrane
Genetic constraint (gnomAD): Loss-of-function variants: 13 observed, 32.54 expected, observed/expected ratio (o/e) 0.4, 90% interval 0.26 to 0.63. The upper end of that interval is the gene's LOEUF score, 0.63, which puts it in group 2 of 6, group 1 being the genes least tolerant of losing a copy. Missense variants: 260 observed, 373.27 expected, observed/expected ratio (o/e) 0.7, 90% interval 0.63 to 0.77. Synonymous variants: 150 observed, 142.66 expected, observed/expected ratio (o/e) 1.05, 90% interval 0.92 to 1.2.
Homologues: Orthologues: chimpanzee OPN5 (99% identical), macaque OPN5 (99% identical), dog OPN5 (97% identical), pig OPN5 (96% identical), mouse Opn5 (95% identical), rabbit OPN5 (93% identical), rat Opn5 (92% identical), guinea pig OPN5 (82% identical), tropical clawed frog opn5 (71% identical), zebrafish opn5 (66% identical), Caenorhabditis elegans nmur-3 (17% identical), Caenorhabditis elegans sro-1 (16% identical). Paralogues in human: OPN4 (27% identical), RRH (25% identical), OPN3 (24% identical), RHO (21% identical), OPN1MW (21% identical), OPN1MW2 (21% identical), OPN1MW3 (21% identical), OPN1LW (20% identical), OPN1SW (17% identical).
Diseases named in the same sentence as OPN5 in open-access papers:
OPN5 is named in the same sentence as 25 diseases in open-access papers, as found by Europe PMC text mining. Sharing a sentence is not in itself a finding about the gene and the disease. The quoted sentences say what the papers report.
myopia (13 papers, 2021 to 2026). "The inhibitory effects of VL on myopia progression are reduced in retina-specific opsin 5 (Opn5) knockout (KO) mice." (PMID 37857760, 2023). "The protective effect of VL on myopia progression required retinal expression of the VL-sensitive atypical opsin, neuropsin (OPN5), and Opn5-expressing retinal ganglion cells with VL prevented experimental myopia in mice." (PMID 36294321, 2022). "OPN5 in human retina has almost the same absorption spectrum as mouse OPN5 and thus suggests great potential for using VL as an option for preventing myopia." (PMID 34031241, 2021). "Considering the known functions of OPN5, it is possible that the action of VL in suppressing myopia involves the retinal circadian clock." (PMID 34031241, 2021). "Our previous study reported that the predusk exposure to VL suppresses myopia progression via OPN5 in mice and observed the effectiveness of this suppression varies depending on the timing of VL exposure, indicating a potential influence on the circadian rhythm regulated by VL and OPN512." (PMID 37857760, 2023). "Additionally, it has been shown that myopia suppression by violet light is mediated by Opn5 in mice." (PMID 37423300, 2023). "In addition, a recent study showed that stimulation of RGCs expressing neuropsin (OPN5) with violet light prevented experimental myopia in mice." (PMID 36313450, 2022). "The requirement for OPN5 also explains why VL has a protective effect on myopia development." (PMID 34031241, 2021). "Stimulation of Opn5 RGCs with short-wavelength violet light prevented experimental myopia in mice." (PMID 34031241, 2021). "In addition, we show that the protective effect of VL on myopia induction requires OPN5 (neuropsin) within the retina." (PMID 34031241, 2021). "The authors showed that lens-induced myopia was ameliorated by exposure to violet light in mice and that the effect of violet light was attenuated in mice with conditional OPN5 knockout in the eye achieved by crossing Chx10-cre mice that express Cre in the eye with OPN5-floxed mice." (PMID 41327490, 2025). "Therefore, exposure to short-wavelength visible violet light may have an important role in preventing myopia progression by activating OPN5 in the retina." (PMID 41327490, 2025). "Furthermore, we found that violet-sensitive retinal ganglion cells (RGCs) via neuropsin (OPN5) may help prevent myopia progression through the maintenance of ChT in LIM mice." (PMID 38792319, 2024). "Therefore, the link between VL exposure-induced EGR-1 and its possible molecular target (Opn5) pathway in the retina may be important for the development of promising myopia control strategies." (PMID 37857760, 2023). "Thus, we considered the possibility that the VL suppression of myopia was dependent on OPN5." (PMID 34031241, 2021). "Recently, non-visual opsins (OPN3, OPN4, and OPN5) have emerged as potentially impacting myopia regulation." (PMID 41620773, 2026). "To date, the roles of EGR-1 and OPN5 in the progression of experimental myopia have not been clearly reported." (PMID 37857760, 2023). "In summary, although the therapeutic roles of EGR-1 and OPN5 have been reported in experimental myopia progression and VL research, their links have not yet been clearly determined." (PMID 37857760, 2023).
breast carcinoma (2 papers, 2022). "In conclusion, our study provided strong evidence that OPN5 splice variants are widely expressed in mouse breast cancer cells." (PMID 36064446, 2022). "The expression of OPN5 in primary and metastatic breast cancer cells of mice was confirmed in our study." (PMID 36064446, 2022). "According to our results, about 60% of total tOPN expression belongs to OPN5 in breast cancer cells isolated from mice." (PMID 36064446, 2022). "In this regard, the present study was designed to investigate the expression of OPN5 in mouse breast cancer cells and its expression level compared to other tOPN isoforms." (PMID 36064446, 2022). "Our study revealed the expression of OPN5 in mouse breast cancer cells for the first time." (PMID 36064446, 2022). "Further research is also needed to determine whether the expression of OPN5 could be used as a biomarker in breast cancer." (PMID 36064446, 2022). "Therefore, this study sought to evaluate OPN5 expression in mouse breast cancer cells." (PMID 36064446, 2022). "Except for in the two breast cancer cell lines, OPN4 and OPN5 were found to be co-expressed in the other 5 cell lines, but the expression patterns differed from those of the previously characterized OPNa, OPNb, and OPNc variants." (PMID 36091936, 2022).
esophageal adenocarcinoma (2 papers, 2022). A malignant tumor with glandular differentiation arising predominantly from Barrett mucosa in the lower third of the esophagus. "OPNa, OPNb, and OPNc variants were first described in glioma, and the two additional splice variants (OPN4 and OPN5) were found in esophageal adenocarcinomas and glioblastomas." (PMID 36091936, 2022). "In 2015, the expression of OPN4 and OPN5 were detected in esophageal adenocarcinoma by Lin etal." (PMID 36064446, 2022).
glioblastoma (2 papers, 2022 to 2023). The most malignant astrocytic tumor (WHO grade IV). "Higher abundance in OPN-a, OPN-c, and OPN-5 occurs in endometrial carcinoma, breast adenocarcinoma, colon adenocarcinoma, and glioblastoma." (PMID 37095438, 2023).
metastatic tumor (2 papers, 2022). "The expression of tOPN and OPN5 was analyzed in the primary and metastatic tumor cells." (PMID 36064446, 2022). "Gene expression analyses revealed that the relative expression of OPNa, OPNb, and OPNc is significantly higher in metastatic tumors compared to primary lesions (p < 0.01), whereas the expression of OPN4 and OPN5 was low in both." (PMID 36091936, 2022).
breast tumor (1 paper, 2022). "In compliance with this research, we detect the expression of OPN5 in mouse breast tumor cells." (PMID 36064446, 2022).
cholangiocarcinoma (1 paper, 2023). A carcinoma that arises from the intrahepatic biliary tree (intrahepatic cholangiocarcinoma) or from the junction, or adjacent to the junction, of the right and left hepatic ducts (hilar cholangiocarcinoma). "OPN-a, OPN-b, OPN-c, and OPN-5 are increased in renal papillary cell carcinoma, cholangiocarcinoma, hepatocellular carcinoma, lung adenocarcinoma, lung squamous cell carcinoma, as well as head and neck cancer." (PMID 37095438, 2023).
melanoma (1 paper, 2022). A malignant, usually aggressive tumor composed of atypical, neoplastic melanocytes. "Taken together, the expression of OPN4 and OPN5 splice variants appears to vary widely in distinct tumor types, but in melanoma, they slightly have a different expression profile than the three predominant splice variants." (PMID 36091936, 2022). "Therefore, in this study, our primary aim was to study the expression profile of five OPN splice variants (OPNa, OPNb, OPNc, OPN4, and OPN5) in different types of malignant melanoma tissues and investigate the association with the clinicopathological features of tumor tissues." (PMID 36091936, 2022). "A significant difference in the expression of OPN5 was observed only between nodular and melanoma metastasis tissues (p ≤ 0.05)." (PMID 36091936, 2022). "The expression of the recently described OPN4 and OPN5 isoforms was shown to be downregulated in the evaluated melanoma subtypes, and OPN4 exhibited a significant negative correlation with Breslow thickness." (PMID 36091936, 2022).
Photophobia (1 paper, 2019). Excessive sensitivity to light with the sensation of discomfort or pain in the eyes due to exposure to bright light. "Nonetheless, role of opn5 in photophobia management might be suspected from the results some recent studies." (PMID 31178682, 2019).
skin cancer (1 paper, 2022). "In a recent study on human skin cancer tissue and cell line, researcher found that OPN5 expression was higher than OPNb and OPNc in normal skin." (PMID 36064446, 2022). "This study also emphasizes the pivotal role of OPN5 in the skin cancer." (PMID 36064446, 2022).
Splenomegaly (1 paper, 2025). Abnormal increased size of the spleen. "This difference in disease level was reflected in the spleen weight of mice from each treatment group such that untreated disease in the VEH-treated mice resulted in CLL-like marked splenomegaly that is significantly reduced with OPN5 treatment." (PMID 40708600, 2025).
cancer (5 papers, 2022 to 2025). A tumor composed of atypical neoplastic, often pleomorphic cells that invade other tissues. "Although both MDSC populations would ideally decrease with effective immunomodulatory anti-cancer therapy, it is encouraging that OPN5 directly impacts M-MDSCs—an aggressively immune-suppressive MDSC population linked to negative outcomes in patients with CLL." (PMID 40708600, 2025). "To test how OPN5 treatment directly modulates MDSC function, we excluded secondary effects of OPN5′s anti-cancer activity by first treating murine-derived MDSCs in ex vivo cultures." (PMID 40708600, 2025). "In a recent work on human OPN-SV the expression profile of osteopontin-4 (OPN4) and osteopontin-5 (OPN5) has been addressed in distinct cancer cell lines." (PMID 36064446, 2022). "We also recently found that OPN-4 and OPN-5 are co-expressed in several human cancer cell lines and tumor tissues, further evidencing their roles in cancer biology, as has been previously found in several reports regarding OPN-a, OPN-b, and OPN-c splice variants." (PMID 36769264, 2023). "There are some studies on other splice variants, but the expression of osteopontin-5 (OPN5) has not been addressed in mouse cancer cells." (PMID 36064446, 2022). "In human cancer cell lines, results indicated that OPN4 and OPN5 transcripts displayed co-expressed in most have been assessed cell lines except for MDA-MB-231 and MCF-7, which only express OPN5." (PMID 36064446, 2022). "OPN5 exhibits modest preference for BD1 (anticancer) over BD2 (antiinflammatory), suggesting that this therapy has lower potential to elicit autoimmune responses in patients with cancer." (PMID 38775157, 2024). "There is evidence for non–cancer-specific T cell exhaustion in the Eμ-TCL1 mouse model, but further studies are needed to determine the antigen specificity and, therefore, antitumor potential of CD8+ T cells following OPN5 treatment." (PMID 38775157, 2024). "Studies emphasize that alternative splicing of osteopontin is not known to occur in mice, and there is no report regarding the investigation of OPN5 in any tumor types or cancer cells in the mouse to the extent of our knowledge." (PMID 36064446, 2022). "Additionally, we show that pharmacological BET inhibition with OPN5 reverses MDSC-mediated immune suppression in preclinical models of CLL, highlighting the translational potential of BET inhibition as an anti-cancer therapeutic simultaneously targeting MDSCs in CLL." (PMID 40708600, 2025).
tumor (3 papers, 2022 to 2025). "Through influencing tumor CLL B-cells, accessory MDSCs, and the T-cells themselves, OPN5 contributes to the revival of CLL-associated T-cells, which can have important implications in tumor control." (PMID 40708600, 2025). "It is concluded that, like other OPN-SVs, OPN5 probably plays an essential role in tumor progression, which requires further investigation in different tumor models." (PMID 36064446, 2022). "It is concluded that, like other OPN-SV, OPN5 probably plays an essential role in tumor progression, which requires further investigation in different tumor models." (PMID 36064446, 2022). "Furthermore, the functional roles of OPN5 in distinct aspects of tumor progression and their interaction with another OPN-SV remain unclear." (PMID 36064446, 2022). "Moreover, once OPN5 can be expressed in lower or higher levels regarding the remaining OPN-SV, these expression profiles provide some clues regarding their functional roles of this variant in tumor progression, which should be further investigated." (PMID 36064446, 2022).
OPN5 also shares sentences with these, for which no sentence is quoted: acute graft versus host disease (1 paper); breast adenocarcinoma (1); colon adenocarcinoma (1); endometrial carcinoma (1); glioma (1); head and neck cancer (1); hepatocellular carcinoma (1); lung adenocarcinoma (1); lung squamous cell carcinoma (1); nodular melanomas (1); renal papillary cell carcinoma (1); retinopathy of prematurity (1).